HMGA1 (high mobility group AT-hook 1)
Diseases named in the same sentence as HMGA1 in open-access papers (continued):
Sharing a sentence is not in itself a finding about the gene and the disease.
ovarian carcinoma (23 papers, 2014 to 2024). A malignant neoplasm originating from the surface ovarian epithelium. "Moreover, we observed the downregulation and copy number deletion of two genes (ERBB3 and HMGA1) in the NR group, which are associated with poor prognosis and tumorigenesis in ovarian cancer." (PMID 39135097, 2024). "Studies note that HMGA1 serves as a useful diagnostic biomarker in ovarian carcinomas." (PMID 30614613, 2019). "To further confirm that HMGA1 promotes DNA repair via the NHEJ pathway, we knocked down BRCA1 and BRCA2 in TYK‐nu ovarian cancer cells to simulate a homologous recombination deficiency (HRD) state." (PMID 39690136, 2024). "Given that olaparib is clinically used to treat cancers with HRD, including ovarian and EC, we examined the sensitivity of HMGA1 to olaparib in HRD ovarian cancer cells." (PMID 39690136, 2024). "In this study, we first elucidated that the aberrant overexpression of MYU promoted ovarian cancer cell proliferation by interacting with miR-6827-5p and upregulating HMGA1 expression." (PMID 36776216, 2023). "In future studies, we will further explore the role of different HMGA1 protein isoforms on ovarian cancer." (PMID 36776216, 2023). "The sensitivity and specificity of HMGA1 in ovarian cancer urine are high, and the detection of HMGA1 level in urine can be used as the basis for the diagnosis of serous ovarian cancer." (PMID 36741380, 2022). "let-7d-5p has been proven to repress viability, migration, and cell cycle progression of ovarian cancer cells by targeting HMGA1." (PMID 34416900, 2021). "The study was based on a 3D culture of A2780, SKOV3, and PA1 ovarian cancer cells, where elevated HMGA1 expression was observed along with expression of stemness markers." (PMID 34439332, 2021). "For instance, HMGA1 is able to regulate chemoresistance in ovarian cancer stem cells and non-small cell lung cancer cells." (PMID 33816494, 2021). "Another study suggests an important role for HMGA1, a chromatin remodeling factor, in ovarian cancer stem cell function." (PMID 34439332, 2021). "We next transfected gradient concentration of HMGA1P6 plasmid into ovarian cancer cells and then evaluated HMGA1 and HMGA2 expression." (PMID 32127525, 2020). "We further demonstrated that HMGA1P6 was one of highly expressed pseudogenes in HGSOC which promoted ovarian cancer aggressiveness through modulating HMGA1/2." (PMID 32127525, 2020). "We further measured HMGA1P6 and HMGA1/2 expression in ovarian cancer cell lines with MYC overexpression or knockdown." (PMID 32127525, 2020). "Collectively, these results indicate that HMGA1P6 acts as a ceRNA to regulate HMGA1/2 expression in ovarian cancer." (PMID 32127525, 2020). "Mechanistically, HMGA1P6 promoted ovarian cancer cell malignancy by acting as a ceRNA (competitive endogenous RNA) that led to enhanced HMGA1 and HMGA2 expression." (PMID 32127525, 2020). "In agreement with our results, HMGA1P6 and HMGA1P7 expression was also upregulated in anaplastic thyroid and ovarian carcinomas and pituitary tumors, where it significantly correlates with HMGA1 overexpression." (PMID 31096664, 2019). "We obtained similar results in human ovarian carcinomas suggesting that HMGA1Ps can regulate HMGA1 protein levels also in vivo." (PMID 25268743, 2014). "The novel ceRNA network composed of MYU, miR-6827-5p, and HMGA1 may provide potential targets and biomarkers for the diagnosis and prognosis of ovarian cancer." (PMID 36776216, 2023). "In addition, in many carcinomas, such as breast, colon, lung, and ovary cancers, the expression level of HMGA1 was found to inversely correlate with the clinical prognosis." (PMID 35406534, 2022).
ovarian carcinoma (continued). "In addition, HMGA1P6 promotes ovarian cancer aggressiveness through modulating HMGA1 and HMGA2." (PMID 32127525, 2020). "In addition, other cancer types in which the expression of HMGA1 is high, including colorectal, pancreatic, and ovarian cancer, could also secrete HMGA1." (PMID 31779212, 2019). "In this context, HMGA1 over-expression was observed in epithelial ovarian carcinomas, while NOTCH1 has been correlated with ovarian cancer development and a poor prognosis." (PMID 29132324, 2017). "We knocked down BRCA1 and BRCA2 in ovarian cancer cells and treated them with olaparib in the presence or absence of HMGA1‐knockdown." (PMID 39690136, 2024).
colon carcinoma (21 papers, 2012 to 2025). "In this issue of the JCI, Luo and colleagues used genetically engineered mouse models to show that high mobility group A (HMGA1) is a critical mediator in the development of colon tumors driven by the loss of the Apc gene." (PMID 39895631, 2025). "Loss of just a single Hmga1 allele is sufficient to decrease tumorigenesis and prolong survival in mice with colon tumors driven by biallelic Apc inactivation." (PMID 39895630, 2025). "Nonetheless, an association between high expression of HMGA1 and increased activity of trabectedin on thyroid and colon carcinoma cells has been also reported." (PMID 38758230, 2024). "In the intestine of transgenic mice, overexpression of Hmga1 leads to hyperproliferation and to the development of abnormal crypts and polyps; furthermore, HMGA1 causes metastatic progression and endows colon cancer cells with stem cell-like abilities." (PMID 31963852, 2020). "While prior studies show that HMGA2 is overexpressed in colon cancer and Hmga2 drives tumorigenesis in mouse models with Let-7 deficiency, we focus on HMGA1 since transcripts are approximately 100-fold higher than HMGA2 in colon cancer datasets (TCGA) and in many other human tumors." (PMID 39895630, 2025). "Notably, Min mice with tissue-specific HMGA1 deficiency developed fewer colon tumors and decreased crypt depth compared with Min mice with intact HMGA1." (PMID 39895630, 2025). "Our scRNA-seq results show that tumor-infiltrating T-lymphocytes increase in the setting of HMGA1 deficiency, suggesting that HMGA1 in colon tumor cells may foster an immunologically “cold” tumor microenvironment to facilitate tumor progression." (PMID 39895630, 2025). "Surprisingly, Min mice with Hmga1 haploinsufficiency had a similar decrease in colon tumor number as Min mice with homozygous Hmga1 loss, suggesting that a relatively modest decrease in HMGA1 within the epithelial compartment alone is sufficient to mitigate tumorigenesis." (PMID 39895630, 2025). "Finally, it has already been shown that HMGA1 overexpression is associated with patients’ poor outcome in several human neoplasias, such as colon carcinomas, pancreatic adenocarcinomas, non-small cell lung cancer and breast tumors." (PMID 31096664, 2019). "Further, silencing HMGA1 disrupts oncogenic properties (proliferation and clonogenicity), while reexpression of ASCL2 partially rescues oncogenic phenotypes in HMGA1-depleted human colon cancer cells." (PMID 39895630, 2025). "Because previous studies from our group and others showed that HMGA1 is highly overexpressed in human colon cancer and required for oncogenic properties in colon cancer cell lines, we sought to assess its role in colon tumorigenesis in vivo." (PMID 39895630, 2025). "Given the link between ASCL2 and early onset colon cancer, further studies to explore HMGA1 and ASCL2 are warranted." (PMID 39895630, 2025). "Further, in human colon cancer, HMGA1 and ASCL2 are coexpressed and upregulated along with downstream Wnt pathway genes." (PMID 39895630, 2025). "Together, our results establish HMGA1 as an epigenetic gatekeeper of Wnt signals and cell state under conditions of APC inactivation, illuminating HMGA1 as a potential therapeutic target in colon cancer." (PMID 39895630, 2025). "Strikingly, most of the Wnt genes upregulated by HMGA1 in our murine model are also upregulated in human colon cancer, including the WNT effectors, ASCL2, AXIN2, CTNNB1, MYC, EPHB2, CD44, and ETS2 and the WNT receptors, LGR5, LRP5, and LRP6." (PMID 39895630, 2025). "In colon cancer, HMGA1 is among the genes most highly overexpressed compared with nonmalignant colon epithelium." (PMID 39895630, 2025). "We found that Hmga1 haploinsufficiency dampens colon tumor development and prolongs survival in 2 models." (PMID 39895630, 2025).
colon carcinoma (continued). "Silencing HMGA1 in 2 human colon cancer cell lines (SW620, SW480) by lentiviral-mediated delivery of short hairpin RNA (shRNA) or CRISPR/Cas9 represses ASCL2, demonstrating that ASCL2 expression depends on HMGA1." (PMID 39895630, 2025). "To dissect HMGA1-dependent changes in the cell of origin for colon tumors, we focused on the epithelial island." (PMID 39895630, 2025). "HMGA1 also upregulates genes involved in an epithelial-to-mesenchymal transition in colon cancer cell lines." (PMID 39895630, 2025). "Restoration of ASCL2 only partially rescues proliferation in colon cancer cell lines with HMGA1 silencing, indicating that HMGA1 regulates additional networks during colon tumorigenesis." (PMID 39895630, 2025). "Consistent with this, in colon tumor stem cells (CTSCs), HMGA1 is expressed at higher levels than in normal and in colon cancer cells." (PMID 31963852, 2020). "Recent studies have found that the role of let-7i-5p is to suppress cellular migration and proliferation via HMGA1 gene targeting in bladder cancer and kallikrein-related peptidase 6 in colon cancer." (PMID 32411089, 2020). "Consistently, HMGA1i-interfered HeLa cells (HMGA1i) show downregulation of these genes, whereas HMGA1-overexpression in several human colon cancer and NIH3T3 cells induces their upregulation." (PMID 26009897, 2015). "First, we demonstrated that HMGA1 is enriched in CTSCs compared with colon tumours and cancer cell lines and is more abundantly expressed in CD133+ cells than in CD133− cells, strengthening its association with tumour-initiating cells." (PMID 24833610, 2014). "We first analysed HMGA1 expression by western blot in normal colonic mucosa (NM), colon cancer, colon cancer cell lines and CTSC lines." (PMID 24833610, 2014). "We observed that HMGA1 is overexpressed in colon tumour stem cell (CTSC) lines compared to normal and colon cancer tissues." (PMID 24833610, 2014). "Here, we report that HMGA1 silencing dramatically affects the survival of colon tumour stem cells and shifts stem cell division to an asymmetric pattern." (PMID 24833610, 2014). "HMGA1 was undetectable in NM, whereas it was expressed in colon cancer (Tumour#3), in 3 colon cancer cell lines (SW48, SW480 and CACO2), and CTSCs (CTSC#18 and CTSC#1.1), which exhibited the highest HMGA1 expression." (PMID 24833610, 2014). "More recently, studies in colon cancer showed that HMGA1 is required for tumor progression and stem cell properties." (PMID 23658826, 2013). "High levels of HMGA1 protein or mRNA were reported in colon cancer cell lines or primary tumors in a small pilot study." (PMID 22276142, 2012). "Taken together, these findings suggest that HMGA1 promotes tumor progression in colon cancer by reprogramming colonic epithelium to a stem-like state." (PMID 22276142, 2012). "Our findings demonstrate for the first time that HMGA1 drives proliferative changes and polyp formation in the intestines of transgenic mice and induces metastatic progression and stem-like properties in colon cancer cells." (PMID 22276142, 2012). "Because recent studies link EMT to epithelial stem cell properties, we sought to determine if HMGA1 regulates EMT genes in colon cancer." (PMID 22276142, 2012). "To determine if HMGA1 is required for tumor progression, we used a preclinical model for metastatic progression in colon cancer." (PMID 22276142, 2012). "We also assessed protein expression in a subset of primary colon tumors with sufficient material and found the highest levels of HMGA1 protein in the high grade, metastatic tumors with undetectable levels in the adjacent normal tissue." (PMID 22276142, 2012). "In colon cancer cell lines from poorly differentiated, metastatic tumors, knock-down of HMGA1 blocks anchorage-independent cell growth, migration, invasion, xenograft tumorigenesis and three-dimensional colonosphere formation." (PMID 22276142, 2012).
colon carcinoma (continued). "To determine how HMGA1 functions in metastatic colon cancer, we manipulated HMGA1 expression in transgenic mice and colon cancer cells." (PMID 22276142, 2012). "In a pilot of 10 primary, high-grade (grade III–IV) colon cancers (a generous gift from Bert Vogelstein), we found that HMGA1 expression was increased in most colon cancer samples (8/11) compared to adjacent normal tissue from the same patient." (PMID 22276142, 2012). "To investigate the functional role of HMGA1 in colon cancer, we inhibited HMGA1 expression in two colon cancer cell lines derived from poorly differentiated (grade 4), metastatic colon cancers (HCT116 and SW480) using an shRNA approach." (PMID 22276142, 2012). "Previous studies identified HMGA1 as a key transcription factor enriched in ES cells, colon cancer, and other aggressive tumors, although its role in these settings is poorly understood." (PMID 22276142, 2012). "To determine if HMGA1 is overexpressed in larger studies of primary colon cancers, we queried gene expression profile analysis of primary colon cancers from six independent studies through the OncomineTM public database (Compendia Bioscience, Ann Arbor, MI)." (PMID 22276142, 2012). "In metastatic colon cancer cells, HMGA1 induces expression of Twist1, a gene involved in embryogenesis, EMT, and tumor progression, while HMGA1 represses E-cadherin, a gene that is down-regulated during EMT and metastatic progression." (PMID 22276142, 2012). "In human colon cancer cells, HMGA1 directly induces ASCL2 by recruiting activating histone marks." (PMID 39895630, 2025). "Elevated expression of HMGA1 was found to require the presence of oncogenic Ras in colon cancer." (PMID 37370109, 2023). "LncRNA H19 is upregulated in colon cancer tissues, and its knockdown represses the migratory and invasive ability of colon cancer cells via sponging miR-138 and promoting the subsequent upregulation of high-mobility group A (HMGA1)." (PMID 33246471, 2020). "High mobility group AT-hook 1 (HMGA1) is inhibited by H19 short hairpin RNA (shRNA) and is promoted by miR-138 inhibitor, and the H19-miR138-HMGA1 pathway plays important roles in mediating the invasion and migration of colon cancer." (PMID 32117736, 2020). "Finally, a significant direct correlation between HMGA1 and SAC genes expression was detected in human colon carcinomas indicating a novel mechanism by which HMGA1 contributes to cancer progression." (PMID 26009897, 2015). "Finally, human colon carcinomas show high SAC gene expression that correlates with HMGA1 protein levels." (PMID 26009897, 2015). "Therefore, human colon carcinoma show SAC gene overexpression that strongly correlates with that of HMGA1, likely contributing to cancer progression." (PMID 26009897, 2015). "Although further work is needed, these results underscore the role of HMGA1 as a key regulator in tumor progression and a stem-like state in colon cancer and suggest that targeting HMGA1 pathways could be beneficial in therapy for colon cancer." (PMID 22276142, 2012). "Here, we report for the first time that the HMGA1 drives proliferative changes and polyp formation in the intestines of transgenic mice and directs molecular pathways important in tumor progression and stem cell properties in human colon cancer cells." (PMID 22276142, 2012). "Our results also suggest that HMGA1 or downstream pathways could be rational therapeutic targets in metastatic, poorly differentiated colon cancer." (PMID 22276142, 2012). "Because HMGA1 is enriched in stem cells and causes changes in the mouse intestine that could be consistent with expansion in the intestinal stem cell compartment, we sought to determine if HMGA1 is involved in stem cell properties in colon cancer cells." (PMID 22276142, 2012). "E-cadherin did not change in the HCT116 colon cancer cells with knock-down of HMGA1, which could reflect stable silencing of E-cadherin in these mesenchymal, highly metastatic colon cancer cell lines." (PMID 22276142, 2012).